LGALS1 (galectin 1)
Diseases named in the same sentence as LGALS1 in open-access papers (continued):
Sharing a sentence is not in itself a finding about the gene and the disease.
tumor (continued). "Galectin-1 emerges as a critical molecular entity in the landscape of PDAC, particularly in its influence on the differentiation of dendritic cells towards a tolerogenic disposition within the tumor microenvironment." (PMID 37958483, 2023). "We demonstrated that LGALS1 is involved in immunosuppression, might be correlated with reduced survival in GBM patients, and that LGALS1 KO in GBM tumor cells can transform the immune landscape." (PMID 37791581, 2023). "In addition, we analyzed the correlation between Galectin-1 expression and overall survival in patients with different HCC tumor grades." (PMID 37433225, 2023). "Galectin-1 may promote NRP-1 expression by activating IL-8 secretion, and then galectin-1 binds to NRP-1 that is highly expressed on the surface of CAFs or PSC, ultimately promoting PDAC tumor immune evasion." (PMID 36428567, 2022). "In the present study, the mRNA expression of five galectins (LGALS1, LGALS3, LGALS4, LGALS8, and LGALS9) is explored in the tumor samples of 56 ovarian carcinoma patients, and the expression fold change was calculated in comparison to 26 adult females with normal ovaries." (PMID 36050693, 2022). "Galectin-1 forms the hypoxic microenvironment and contributes to the immune evasion of PDAC tumor cells by enhancing HIF activity, promoting the formation of ADAM10, inducing the low expression of NKG2D, and reducing the activity of NK cells in PDAC, which results in poor proliferation of NK cells." (PMID 36428567, 2022). "For instance, galectin-1, galectin-3, and CD47 are expressed on the tumor cell membrane." (PMID 36382024, 2022). "The tumor center was characterized by a higher abundance of LMNA (two proteoforms), dihydropyriminidase-related protein (DPYSL3), tubulin beta (TUBB), myosin light chain 3 (MYL3), and galectin-1 (LGALS1)." (PMID 35512017, 2022). "Taking CD4+ Treg cells and CD8+ cytotoxic T cells as examples, Treg cells derived from tumor tissues showed higher expression of LAYN, LGALS1 and TNFRSF1B, and cytotoxic T cells derived from tumor tissues showed higher expression of TNFRSF9 (encoding 4-1BB), LAYN and CTLA4." (PMID 36104333, 2022). "LGALS1, B4GALT6, and GALNT11 were upregulated and MGAT5, MAN1A1, MANBA, LUM, GALNT1 and 7, HAPLN3, and ST6GALNAC5 were downregulated in Fra-2 cl 1 select primary tumours, while MGAT4A was upregulated." (PMID 34693476, 2022). "In addition, high expression of c-Jun N-terminal kinase (JNK)/CJun/activator protein 1 (AP-1) in PDAC induces apoptosis of T cells, and galectin-1 promotes T cell apoptosis through activation of the JNK/C-Jun/AP-1 pathway, promoting PDAC tumor immune evasion." (PMID 36428567, 2022). "We speculate that NCAPG might interact with LGALS1 to upregulate SPARC, leading to activate EMT signaling and augment tumor-derived vascular permeability." (PMID 35180865, 2022). "Anti-VEGF-A refractory tumors enhanced galectin-1 secretion together with its increased binding to neovascular endothelial cells due to altered glycosylation patterns on VEGFR2, leading to galectin-1-driven angiogenesis and tumor progression." (PMID 34943209, 2021). "Furthermore, studies also reported that interaction of galectin-1 and VEGFR2 activate VEGF-like signaling in tumor angiogenesis." (PMID 33803224, 2021). "Meantime, in non-TNBC lymph node metastases, LGALS1 expression induced the apoptosis of activated T cells and promoted the angiogenesis of metastatic tumor tissue by interacting with CD69." (PMID 34611125, 2021). "Perhaps galectin-1 could be a more appropriate and effective target, even more so if used in combination with targeted therapy such as CAR-T cells to increase tumor infiltration." (PMID 34140956, 2021). "It has been reported that protein–protein interaction could affect the tumor-promotion function of galectin-1, implying that the interaction of FAM289 with some proteins may result in the gain of its tumor-promoting properties in GBM." (PMID 31492191, 2019).
tumor (continued). "On the other hand, the galectin-1-rich tumour stroma was not proved as a biomarker of poor patient survival." (PMID 30925774, 2019). "Galectin-1 could regulate acinar-to-ductal metaplasia by promoting Hedgehog pathway signaling in PDAC cells and tumor-stroma crosstalk." (PMID 31832021, 2019). "Expression of galectin-1 and galectin-3 in tumor cells can block apoptosis; when shed in the tumor microenvironment, both galectins induce T cell apoptosis via CD45 and CD7 binding on T cell surface, favoring, indeed, tumor immune escape." (PMID 30935099, 2019). "Nevertheless, in the analysis of subgroup, the elevated galectin-1 expression was considered as a bad prognostic marker in cancerous patients for OS, regardless of the kind of tumor, ethnicity, the kind of analysis and the method of obtaining HR." (PMID 30087582, 2018). "It was not possible to assess the level of galectin-1 expression in the standardized manner at the most invasive part of the tumor, which is the region expected to have an increased amount of CAFs and remodeled ECM." (PMID 30140386, 2018). "Based on co-expression analysis in the TCGA CRC database, COX7A1 was highly co-expressed with LGALS1 coding for galectin-1 (LGALS1/galectin-1), a lectin that is upregulated in the tumor stroma and can inhibit immune response through CD45 protein phosphatase activity (Spearman’s correlation = 0.84)." (PMID 30140386, 2018). "Nevertheless, the expression of galectin-1 and integrin α5β1 in tumor cells had no statistical difference between these two groups." (PMID 28842515, 2017). "Although the role of galectin-1 in ocular angiogenesis has not been established, accumulating evidence has demonstrated that galectin-1 plays a pivotal role in modulating tumor angiogenesis." (PMID 28055102, 2017). "Moreover, while most studies have examined one galectin at a time, focusing largely on galectin-1 and galectin-3, it is now well established that normal and tumor cells express more than one galectins, and that multiple galectins could be released in the tumor microenvironment (TME)." (PMID 26933916, 2016). "Although the question of which source of galectin-1 (tumour hepatocytes or HSCs) contributes more to the progression of HCC has not been answered definitively, our results suggested that HSC-derived galectin-1 promotes HCC progression at least in part by affecting T cells." (PMID 27494859, 2016). "Furthermore we studied the impact galectin-1 has on the metabolic activity of MCF-7 and T-47D cells in a homotypic three-dimensional spheroid cell culture model mimicking a micro tumour environment." (PMID 27825375, 2016). "The H-scores for galectin-1 expression were found to be significantly higher in the irradiated tumor tissue in comparison to the non-irradiated or benign breast tissue." (PMID 27223428, 2016). "In conclusion, we described that trabectedin affected genes and microRNAs involved in tumor progression and metastatic processes, reflecting data previously obtained at macroscopically level; in particular, we identified SYK and LGALS1 as new putative targets of trabectedin." (PMID 27902465, 2016). "We did not observe a significant decrease in the galectin-1 serum levels upon surgical resection of the tumor." (PMID 26137448, 2015). "Galectin-1 expressing cells were not abundant in the tumor epithelium, but when present the majority was CD163+." (PMID 26066796, 2015). "Since galectin-1 was practically always expressed by tumor infiltrating immune cells and galectin-3 among non-tumor cells by CD163+ macrophages, the galectin-1/3 double positive cells are expected to be tumor epithelium infiltrating CD163+ macrophages." (PMID 26066796, 2015).
tumor (continued). "Since tumor cell expression of galectin-1 and -9 was generally low or absent, galectin-1 and -9 in tumor epithelial fields were predominantly expressed by tumor epithelium infiltrating immune cells." (PMID 26066796, 2015). "Galectin-1 immunohistochemical staining of the U87 galectin-1 clone xenografts were ubiquitously positive, without discernable overexpression at the tumor-brain interface." (PMID 22583806, 2012). "Nonetheless, immunohistochemistry showed that unlike the multi-compartment intracellular and extracellular galectin-1 expression seen in shControl -BD11 tumours, for -BD11 tumor cells transfected with the shGALSN1 vector, galectin-1 expression was restricted to the nucleus." (PMID 21779348, 2011). "Moreover, we found that the interplay distances of LGALS1‐PTPRC LRI were closer in non‐responders between iCAFs and CD8+ Tex cells, which could possibly drive T cell exhaustion and reduce anti‐tumour immunity." (PMID 40375605, 2025). "According to one study, galectin-1 could promote tumor proliferation and medication resistance by activating the P38 MAPK pathway, which in turn increases the expression of Cox-2, which augments tumor angiogenesis and resistance to apoptosis." (PMID 40052129, 2025). "It focused on the mechanisms related to galectin-1 in helping PDAC cells accomplish immune evasion by forming an immunosuppressive microenvironment, remodeling the extracellular matrix to form a fibrous barrier, and ultimately participating in promoting angiogenesis and tumor cell metabolism." (PMID 36428567, 2022). "Moreover, we identified possible communications mediated by heparanase and galectin-1 which could regulate ECM remodeling and tumor immune microenvironment (TIME) reshaping." (PMID 36189263, 2022). "Glycosylation of tumor proteins, LGALS1 for example, may generate neo-antigens that can serve as novel targets to enhance specific T cell immunity against tumor." (PMID 34768716, 2021). "These protumorigenic effects relied on tumor-derived but not host-derived galectin-1." (PMID 35008740, 2021). "Also, research on galectin-1 has mainly focused on its role in tumor and immune cells and not in fibroblasts." (PMID 30140386, 2018). "Here we assessed the ability of non-peptidic galectin-1 inhibitor OTX008 to improve tumor oxygenation levels via tumor vessel normalization as well as tumor growth inhibition in two human HNSCC tumor models, the human laryngeal squamous carcinoma SQ20B and the human epithelial type 2 HEp-2." (PMID 29232825, 2017). "Moreover, tumor-related process such as invasion, angiogenesis, proliferation, MMP2, MMP9 expression, and EMT process could be induced by galectin-1 in PDAC." (PMID 29254283, 2017). "With regard to proteins’ expression in stromal cells, galectin-1 and integrin α5β1 protein expression were also markedly down-regulated after cisplatin-based NACT when compared with their matched prechemotherapy tissues, consistent with their expression in tumor cells." (PMID 28842515, 2017). "Therefore, we investigated whether human HSCs express galectin-1 and whether galectin-1 contributes to HSC-mediated immunomodulatory functions and tumour immune privilege in HCC." (PMID 27494859, 2016). "The present study is supported by recent findings on elevated expression of stromal galectin-1 in clinical samples of TNBC and our ongoing findings on stromal targeting of radiation induced galectin-1 by the anginex-conjugated arsenic-cisplatin loaded liposomes using a novel murine tumor model." (PMID 27223428, 2016). "Glycome remodeling of the EC surface facilitated binding of galectin-1 to N-glycans expressed on VEGFR-2 in anti-VEGF refractory tumors but inhibited galectin-1 binding in anti-VEGF sensitive tumors, which explains the proliferation of certain tumor types during anti-VEGF treatment." (PMID 27649167, 2016).
tumor (continued). "Galectin-1 likely acts as a scaffold for vessel growth and vascular network formation by establishing physical connections between vascular endothelial cells and the ECM in the tumor microenvironment, which provide the necessary physical support for neovasculature." (PMID 27649167, 2016). "Our studies have also elucidated the radiation-induced galectin-1 surge to be more pronounced in the murine TNBC model developed from orthotopic implants of TTA comprised of tumor cells, endothelial cells and fibroblasts than the orthotopic implants of tumor cell only–spheroids." (PMID 27223428, 2016). "A few years ago we reported about the synthesis and inhibitory properties of a small library of lactosylthioureidocalixarenes and found that the cone derivatives I and III were able to efficiently inhibit the adhesion of Gal-3 to tumor cells in vitro, but not that of galectin-1." (PMID 25161726, 2014). "Therefore we took great interest in identifying the relative galectin-1 and galectin-3 mRNA concentration by using tumor and non-tumor tissue from the same patient as reference." (PMID 24708743, 2014). "In addition, Galectin-1 was negative in non-metastatic peripancreatic lymph nodes and positive in tumor metastatic peripancreatic lymph nodes." (PMID 24595374, 2014). "Recent studies have verified that Galectin-1 and other proteins identified in -BD11 ECM, e.g. aminopeptidase-N annexin-A2 or nucleolin, can serve as tumour targets, with evidence that combined targeting of perivascular and endothelial cells can enhance anti-tumour treatment." (PMID 21779348, 2011). "Furthermore, in vivo administration of Nor led to a reduction in tumor growth, weight, and secretion of LGALS1 and IGFBP7 in HGC‐27‐formed xenograft models, alongside decreased proliferation index (Ki‐67), reduced CD31‐positive microvessels, and altered levels of AKT phosphorylation and EMT markers." (PMID 40995693, 2025). "Furthermore, miR-22 suppresses tumor proliferation, tumorigenesis, and metastasis by targeting proteins, including Protein Kinase C Inhibitor Protein-1 YWHAZ, cluster of differentiation 147 (CD147), galectin-1 (LGALS1), cyclin A2 (CCNA2), and specificity protein 1 (SP1)." (PMID 39953622, 2025). "However, in a murine colorectal model, targeting galectin-1 did not lower the frequency of CD4+CD25+ Tregs in the tumor, spleen as well as tumor-draining lymph nodes, whereas the proportion and immunosuppressive properties of CD8+CD122+PD-1+ Tregs were reduced." (PMID 37047471, 2023). "Interestingly, the anti-correlation is strongest when the LGALS1 and LAMC1 expression levels are analysed together, suggesting that their combined expression analysis may better predict the success of H-1PV infection against a certain tumour." (PMID 35632759, 2022). "However, galectin-1 levels did not correlate with tumor stage." (PMID 32055023, 2020). "Recent preclinical studies have unveiled novel therapies such as anti-cathepsin antibodies, galectin-1 blockade and anti-OX40 agonistic antibodies, which may be utilised as adjuvant therapies to modulate the tumour microenvironment and permit more ferocious anti-tumour immune response." (PMID 32645977, 2020). "Although it was considered that TDG is a non-selective blocker for galectin-1, TDG treatment did not induce any additional tumor-suppressive effects in Lgals1−/− mice." (PMID 36873388, 2023). "By immunohistochemical staining, we could confirm some of these gene products like MTA2, ESAM, and LGALS1 in primary tumour and in metastasized cells in the lung of the two clones, but CTTN only in primary tumour sections not in metastatic cells of the lung." (PMID 34693476, 2022). "The lower level of LGALS1 expression in LBT003 could thus, at least in part, explain the phenotypic differences between LBT003 and the other GSCCs in the zebrafish avatar model (more GAMs situated closer to the tumor), as well as the general lack of macrophage polarization in the co‐culture model." (PMID 37791581, 2023).
cancer (204 papers, 2005 to 2026). A tumor composed of atypical neoplastic, often pleomorphic cells that invade other tissues. "Galectin-1 and Galectin-3 modulate immune checkpoint pathways and cancer-associated fibroblast activation, whereas Galectin-9 interacts with TIM-3 to induce T-cell exhaustion." (PMID 42129932, 2026). "This study explores the role of Galectin-1, a protein linked to cancer progression, in resistance to enzalutamide." (PMID 39941722, 2025). "Galectin-1 (Gal-1), a galectin family member, influences various cellular processes and is linked to cancer proliferation, splicing, and metastasis." (PMID 39941722, 2025). "Galectin-1 shows increased expression in various carcinomas, and this is associated with a poor prognosis." (PMID 39996781, 2025). "LGALS1, a gene encoding galectin-1 (Gal-1), serves as a potential therapeutic target for cancer treatment." (PMID 38560563, 2024). "Galectin‐1, encoded by the LGALS1 gene, is an important immunosuppressive molecule across cancer types." (PMID 38545824, 2024). "Cancer cell-derived galectin 1 causes overexpression of TDO2 that induces enhanced synthesis of Kyn, a suppressor of dendritic activity." (PMID 38313431, 2023). "The contribution of galectin-1 to inflammation was initially described as a suppressor of cancer-associated inflammation." (PMID 36873388, 2023). "Meanwhile, galectin-1 also interacts with cancer-associated fibroblasts (CAFs) and PSCs, creating a fibrotic barrier that blocks the entry of immune drugs and immune-related cells." (PMID 36428567, 2022). "Previous several studies have revealed that galectin-1 is associated with poor prognosis in numerous human cancers." (PMID 34201887, 2021). "This lectin family possesses a number of biological activities related to the development and progression of cancer, which is primarily associated with galectin-1 (Gal-1) and galectin-3 (Gal-3)." (PMID 34206141, 2021). "Galectin-1 overexpression in cancer associated fibroblasts (CAFs) is correlated with poor prognosis in several types of cancer, including prostate cancer." (PMID 31013716, 2019). "A substantial amount of work on the immunoregulatory activity of galectin-1, and indeed the other members of the galectin family, has been conducted in the context of cancer and associated illnesses." (PMID 29075269, 2017). "Galectin-1, encoded by the LGALS1 gene, contributes to cell adhesion/proliferation and immunosuppression in a variety of cancer cells and regulatory T lymphocytes, respectively." (PMID 29170525, 2017). "Galectin-1 also promotes cancer evasion of the host's immune response by causing DC anergy and T cell apoptosis." (PMID 27050278, 2016). "Galectin-1 has already been implicated in the modulation of several processes required for cancer development, such as cancer stem cell increase and cancer metastasis." (PMID 27050278, 2016). "Examination of the stroma associated with the carcinoma cells demonstrated that it was positive for galectin-1 immunostaining in a large majority of samples (score 3–6 in 81 of 110 cases)." (PMID 26589590, 2015). "Galectin‐1, encoded by LGALS1 gene, is a critical immunosuppressive molecule across cancer types." (PMID 38545824, 2024). "In particular, the metastatic ecosystem was found to feature remarkable reprogramming of immunosuppressive cells such as FOXP3+ Treg cells, LAMP3+ tolerogenic DCs, CCL18+ M2‐like macrophages, RGS5+ cancer‐associated fibroblasts (CAFs), and LGALS1+ microglial cells." (PMID 36529697, 2023). "The galectin family (Galectin-1, -2, -3, -4, -7, -8, and -9) may be associated with cancer progression." (PMID 37433225, 2023). "Galectin-1 and Galectin-3 overexpression has been widely associated with worse outcomes in many cancers, in which they can be expressed by both cancer cells as well as non-cancer stromal cells." (PMID 36430839, 2022). "Indeed, knockdown/out of LGALS1, the gene encoding galectin-1, strongly decreases the ability of H-1PV to infect and kill cancer cells." (PMID 35632759, 2022).